ESR1 (estrogen receptor 1)
Diseases named in the same sentence as ESR1 in open-access papers (continued):
Sharing a sentence is not in itself a finding about the gene and the disease.
premature ovarian failure (10 papers, 2012 to 2026). "Several studies have reported that ESR1 polymorphism is associated with primary ovarian failure (POF)." (PMID 35707481, 2022). "Interestingly, several commonly upregulated genes were observed across cell types, including PTEN, TGFBR2, ATG7, and ESR1, which are implicated in primary ovarian insufficiency." (PMID 41243550, 2026). "Kaempferol notably promoted ESR1 expression in the ovaries tissue of rats with premature ovarian failure." (PMID 38780500, 2024). "The occurrence of FSHR, INHA, ESR1, and BMP15 gene polymorphisms has also been reported to be associated with various reproductive diseases, including primary ovarian insufficiency (POI), pregnancy loss, and preeclampsia." (PMID 37239044, 2023). "We examined SNPs in FSHR, INHA, ESR1, and BMP15, which have been associated with primary ovarian failure." (PMID 37239044, 2023). "In today's industrialized societies, however, the effects of the ESR1 genotype manifest as a successful outcome in women undergoing IVF or predisposing to premature ovarian failure, or exerting a protective effect against azoospermia or idiopathic oligospermia in men." (PMID 22532853, 2012).
pulmonary fibrosis (10 papers, 2019 to 2024). Chronic progressive interstitial lung disorder characterized by the replacement of the lung tissue by connective tissue, leading to progressive dyspnea, respiratory failure, or right heart failure. "Although ESR-1-/- mice and surgical ovariectomy confirm estrogen’s profibrotic capacity in lung fibrosis, it is worth noting that Th17 cell differentiation is reduced due to the transcription factor ERα‘s ability in relation to the STAT3 promoter." (PMID 36899902, 2023). "For example, TGF-β1 (a central factor in the development of pulmonary fibrosis) inhibits the expression of estrogen receptors, especially estrogen receptor alpha (ESR1) in human bronchial epithelial cells." (PMID 35563849, 2022). "Moreover, the activation of ESR1 has been found to inhibit the proliferation of pulmonary myofibroblasts, thereby alleviating pulmonary fibrosis." (PMID 39771125, 2024). "A prior study noted increased ESR-1 expression in human IPF lung samples and that the chemical inhibition of ESR-1 results in reductions in bleomycin-induced pulmonary fibrosis in male mice." (PMID 36899902, 2023). "Because transcription factor ESR-1 (alpha subunit of ESR) was identified as binding to the STAT3 gene in CD4+ T cells, we investigated the role of the ERα subunit in profibrotic cytokine expression using a murine model of bleomycin-induced lung fibrosis in WT and ESR-1 knockout (ESR-1-/-) mice." (PMID 36899902, 2023).
Abdominal obesity (9 papers, 2009 to 2025). Excessive fat around the stomach and abdomen. "Deletion of ESR1 in VMN neurons produces hypometabolism and abdominal obesity, while elimination of ESR1 in pro-opiomelanocortin (POMC) neurons produces hyperphagia." (PMID 39911518, 2025).
carcinoma in situ (9 papers, 2010 to 2026). "Elevated ESR1 expression has been observed in atypical ductal hyperplasia and in situ carcinoma, suggesting that deregulation of the ESR1 expression level may be implicated in early pathogenic changes during breast tumorigenesis." (PMID 34831189, 2021).
Lipedema (9 papers, 2021 to 2026). Disorder of adipose tissue characterized by symmetric and bilateral enlargement of the lower extremities due to abnormal deposition of subcutaneous fat often in obese women. "mRNA expression of the estrogen receptor, ESR1, shows a tendency of upregulation in lipedema compared to healthy thigh-SVF, although without significance (p = 0.075)." (PMID 35625899, 2022).
multiple myeloma (9 papers, 2012 to 2025). "The most relevant entities predicted by paclitaxel in the four tasks are P00372 (ESR1), multiple myeloma, dysaesthesia, and cobicistat." (PMID 37956212, 2023). "The ESR1, multiple myeloma, and dysaesthesia have almost no drugs shared with paclitaxel, which show that these results cannot be effectively predicted by GNNs that relying on the pairwise links." (PMID 37956212, 2023). "However, a study performed in non-hyperdiploid multiple myeloma proposed that ESR1 contributes to cell cycle dysregulation, thus affecting the transcription of several downstream genes including E2F1." (PMID 28806978, 2017).
pulmonary hypertension (9 papers, 2015 to 2025). Increased pressure within the pulmonary circulation due to lung or heart disorder. "It was demonstrated that ESR1 plays an important role in pulmonary arterial hypertension." (PMID 34627325, 2021).
scoliosis (9 papers, 2015 to 2026). A congenital or acquired spinal deformity characterized by lateral curvature of the spine. "Taken together, these results suggest that inactivation of ESR1 signaling asymmetrically in the para-spinal muscles increases the susceptibility to scoliosis in vivo." (PMID 37185898, 2023). "We next investigated whether asymmetric inactivation of ESR1 signaling in para-spinal muscles could increase the susceptibility to scoliosis in a mouse model." (PMID 37185898, 2023). "We next went on to test whether the inactivation of ESR1 signaling cascade increased the susceptibility to scoliosis in vivo using mouse model." (PMID 37185898, 2023). "In conclusion, the homozygous PP genotype of ESR1 was associated with a higher risk of scoliosis (PP vs. Pp+pp, p=0.006; OR: 2.37; 95% CI: 1.27 – 4.43) and the presence of the P allele alone (P vs. p, p = 0.045; OR: 1.48, CI: 1.01 - 2.17) could be considered as susceptibility factor to IS." (PMID 27275235, 2015). "The imbalance of ESR1 signaling in the para-spinal muscles induces scoliosis in mice, while reactivation of ESR1 signaling at the concave side by an FDA approved drug Raloxifene alleviates the curve progression." (PMID 37185898, 2023). "When compared with the ESR1 symmetry group, patients in the ESR1 asymmetry group showed significantly more severe scoliosis (p = 0.041), more hypoplastic concave paraspinal muscle (p = 0.015), and more muscular fatty infiltration in the concave side (p = 0.034)." (PMID 39600965, 2024). "The asymmetry of ESR1 expression might be related to the asymmetry of muscular load on either side of scoliosis." (PMID 35627124, 2022). "The ESR1 expression might be related to the muscular load on either side of scoliosis." (PMID 35627124, 2022). "The expression level of ESR1 decreased in muscle stem/progenitor cells at the concave side in AIS patients, which resulted in differentiation defects and aggravating scoliosis." (PMID 37185898, 2023). "We built a scoliosis mouse model by inhibiting ESR1 activity at one side of the para-spinal muscle, and reactivation of ESR1 by an FDA approved drug Raloxifene at the concave side greatly alleviates the progress of scoliosis." (PMID 37185898, 2023).
type 1 diabetes (9 papers, 2010 to 2025). "The Pvull CC variant of the ESR1 gene showed correlations with less inflammatory and angiogenic activity in girls with type-1 diabetes, while the cardiac and metabolic findings were more serious." (PMID 41514592, 2025). "ESR1 gene upregulation was observed in the blood of children with type-1 diabetes compared with control cases." (PMID 41514592, 2025). "ESR1 gene mutations do not directly correlate with type-1 diabetes." (PMID 41514592, 2025). "In conclusion, studies on ESR1 and CYP19A gene mutations in type-1 diabetes cases could not find direct correlations with either metabolic disorders or autoimmune processes." (PMID 41514592, 2025).
cervical squamous cell carcinoma (8 papers, 2015 to 2025). A squamous cell carcinoma arising from the cervical epithelium. "It has been shown that there are ESR1 mutations in patients with cervical squamous cell carcinoma." (PMID 39206151, 2024). "Moreover, it was found that the phosphorylation of MAPK1/MAPK3 was correlated with tumor growth in OSCC, the methylation of ESR1 promoter was associated with squamous cell cervical cancer, and the activation of FYN kinase was related to OSCC." (PMID 26064958, 2015). "Another study that analyzed cervical squamous cell carcinoma tissue samples found that the expression level of CYP19A1 was upregulated and ESR1 was downregulated in cancer." (PMID 40565012, 2025). "The expression levels of CYP19A1 and lncRNA SRA were upregulated, while those of ESR1 and lnc-CCDC170–4:1 were downregulated in cervical squamous cell carcinoma tissue." (PMID 39206151, 2024). "This study investigated the expression of lnc-CCDC170–4:1, ESR1 (estrogen receptor 1), lncRNA SRA, and CYP19A1 (aromatase) in cervical squamous cell carcinoma tissues, as well as their relationship with the clinical characteristics of patients." (PMID 39206151, 2024). "In contrast, low expression levels of ESR1 mRNA were found in bladder urothelial carcinoma (BLCA), cervical squamous cell carcinoma and endocervical adenocarcinoma (CESC), liver hepatocellular carcinoma (LIHC), testicular germ cell tumors (TGCT), and uterine carcinosarcoma (UCS) samples." (PMID 34322374, 2021).
fibrosis (8 papers, 2012 to 2025). the formation of excess fibrous connective tissue in an organ or tissue in a reparative or reactive process. "In contrast, fEsr1+/+ Aromhum mice exhibited significantly higher LAM fibrosis than both ESR1-depleted fEsr1–/– Aromhum mice and the fEsr1+/+ WT controls." (PMID 39903526, 2025). "TNF was linked to three toxicity-related lists generated by IPA: “Cardiac Fibrosis,” “Cardiac Hypertrophy” and “Cardiac Necrosis/Cell Death” and among them “Cardiac Hypertrophy” was shared between TNF and ESR1." (PMID 32903789, 2020).
gallstones (8 papers, 2012 to 2025). Solid crystalline precipitates in the biliary tract, usually formed in the gallbladder, resulting in the condition of cholelithiasis. "Detailed haplotypes analysis suggested that ESR1 T rs2234693G rs9340799C rs1801132 have significant association in conferring risk for both gallstones [OR = 2.2] and GBC [OR = 3.0]." (PMID 22808109, 2012). "The results of the studied three polymorphisms of ESR1 revealed that distribution of T,G,C haplotypes was significantly higher in gallstone patients (25.1% v/s 13.7) in comparison to controls and was conferring high risk for gallstone disease (p = 0.0012; [OR], 2.2)." (PMID 23577061, 2013). "Furthermore, the prolithogenic action of estrogens was blocked by ESR1-selective antagonists, suggesting that ESR1 is the specific estrogen receptor pathogenically linked to gallstone formation." (PMID 22132343, 2012). "In other study ESR1 polymorphic variants: IVS1-397C > T, ESR1 IVS1-351A > G and ESR2-789 A > C correlated with GBC risk, mediated through gallstone dependent pathway." (PMID 32024900, 2020). "This indicates that GPER1 produces a synergistic lithogenic action with ESR1 to enhance E2-induced gallstone formation." (PMID 33281743, 2020). "Our multi-analytic approach revealed that the combination of genotypes of respective polymorphisms as ESR1 IVS1-397 variant, ABCG8 145 variant, ESR1 IVS1-351 variant and ADRB3 190 variant pose a significant risk for developing gallstone." (PMID 23577061, 2013). "Using gonadectomized gallstone-resistant male or female AKR mice fed with a lithogenic diet in the presence of ESR-selective synthetic estrogens has shown a correlation between gallstone formation and hepatic ESR1 upregulation." (PMID 22132343, 2012). "Using multi-analytical approaches, our study showed important role of ESR1 IVS1-397C>T, ESR1 IVS1-351A>G, and ESR2-789 A>C variants in GBC susceptibility and the risk appears to be mediated through gallstone dependent pathway." (PMID 22808109, 2012). "However, gallstones can be completely prevented in E2-treated ESR1 knockout mice even on the lithogenic diet." (PMID 33281743, 2020). "Furthermore, on subdividing the study groups on the basis of gender we observed that ESR1 IVS1-397C>T and ADRB3 -190 T>C conferred increased risk for gallstones in female gender." (PMID 23577061, 2013). "The association between ESR1 polymorphisms and risk of GBC/gallstones are biologically credible." (PMID 22808109, 2012). "On performing detailed analysis of the haplotypes, we found that the gallbladder carcinoma and gallstones subjects who carry ESR1 haplotypes IVS1-397T, IVS1-351G, Ex4-122C conferred increased risk for both GBC and gallstones indicating that ESR1 haplotype as a risk factor." (PMID 22808109, 2012). "On comparing the genotype frequency distribution in gallstone and GBC patients with that of healthy subjects, the homozygous variant genotypes of ESR1-397TT (rs2234693) polymorphism showed significant risk for developing gallstone [odds ratio: OR = 2.9] and GBC [OR = 1.8] respectively." (PMID 22808109, 2012). "Therefore, in the present study, we investigated a panel of 6 well-studied polymorphisms in ESR1, ESR2 and PGR genes in a case–control design involving 410 GBC patients, 230 gallstone patients and 220 cancer/gallstone-free controls from North India." (PMID 22808109, 2012). "However, the variant-containing genotypes (DI+II) of PGR (rs1042838) showed low risk in both GBC [OR = 0.4] and gallstone patients [OR = 0.4].On performing the MDR analysis, ESR1 IVS1-397C>T, ESR1 IVS1-351A>G, and ESR2-789 A>C yielded the highest testing accuracy of 0.634." (PMID 22808109, 2012). "Overall, these studies have established a novel concept that GPER1 is involved in E2-dependent lithogenic actions, working independently of ESR1, as both GPER1 and ESR1 can promote the formation of E2-induced gallstones through different pathways." (PMID 33281743, 2020).
gallstones (continued). "In conclusion, our study showed that ESR1 IVS1-397C>T (rs2234693), ESR1 IVS1-351A>G (rs9340799), ESR2 -789 A>C (rs1271572) polymorphisms and their higher-order interactions may confer increased risk of gallbladder carcinoma, probably through gallstone mediated pathway." (PMID 22808109, 2012). "In this circumstance, previous evidence has shown that inhibition of ESR1 or GPER1 alone is not sufficient to completely prevent gallstone formation." (PMID 33281743, 2020). "Furthermore, the ESR1-selective agonist propylpyrazole, but not the ESR2-selective agonist diarylpropionitrile, promotes hepatic cholesterol output, leading to cholesterol-supersaturated bile and gallstones." (PMID 33281743, 2020).
Ovarian cyst (8 papers, 2014 to 2023). The presence of one or more cysts of the ovary. "A human case study reported a female patient with a homozygous mutation in the ESR1 gene responsible for ERα expression with a small uterus and ovarian cysts." (PMID 35885010, 2022).
pancreatic adenocarcinoma (8 papers, 2014 to 2024). "A previous study mentioned that ESR1 is also expressed in a subset of pancreatic adenocarcinoma, most notably in mucinous tumors." (PMID 36531045, 2022).
prostate (8 papers, 2014 to 2022). "SR1 is a receptor for oestrogen, which can activate ESR1 to promote normal prostate development and gene expression in prostate disease." (PMID 36330452, 2022). "ESR2 is regulated by AR and interacts with ESR1 to regulate prostate carcinogenesis through the modulation of genes involved in cell proliferation and apoptosis." (PMID 31523634, 2019).
prostate adenocarcinoma (8 papers, 2014 to 2024). "The gene-phenotype connectivity liaised by naringenin revealed that the regulation of ESR1 by naringenin might be a major driver for the chemoprotective salutary effects on prostate adenocarcinoma." (PMID 30918758, 2019).
stomach adenocarcinoma (8 papers, 2017 to 2026). "The other six hub genes have no gene mutation records in STAD-related research, but HDAC1 and ESR1 genes have been confirmed to be related to the occurrence and prognosis of gastric adenocarcinoma, associated with the patients’ DFS and OS." (PMID 35686089, 2022). "GEPIA2 analysis showed that the expression of ESR1 was correlated with the OS of stomach adenocarcinoma." (PMID 35686089, 2022). "Our results showed that the level of ESR1 was increased in gastric adenocarcinoma patients." (PMID 35686089, 2022). "GEPIA2 analysis showed that ESR1 expression was closely correlated with OS and DFS in gastric adenocarcinoma (P < 0.05)." (PMID 35686089, 2022). "In addition, we found that the expression of ESR1, HDAC1, and CLTC genes in patients with stomach adenocarcinoma may be related to poor prognosis and lower overall survival." (PMID 35686089, 2022).
cervical tumor (7 papers, 2015 to 2024). "In this study, we found that the level of B cells infiltrated in cervical tumor was positively correlated with high expression of ESR1." (PMID 34784845, 2021).
endometrial stromal sarcoma (7 papers, 2014 to 2025). "Similarly, ESR1 mutations in endometrial stromal sarcoma may predict primary or acquired resistance to hormonal therapy, as shown in breast cancer." (PMID 35705558, 2022).
gestational diabetes (7 papers, 2016 to 2025). Carbohydrate intolerance first diagnosed during pregnancy. "ESR1 and islet β apoptosis are closely related, and it is also one of the biological indicators for clinical diagnosis of gestational diabetes in early pregnancy." (PMID 36452059, 2022). "In omental adipose tissue from women with gestational diabetes mellitus miR-222-3p expression was found upregulated; besides that, miR-222-3p expression was negatively correlated with estrogen receptor 1 (ESR1) and GLUT4 contents and positively correlated with serum estradiol levels." (PMID 28428964, 2017).